EDRF1 (erythroid differentiation regulatory factor 1)
Description:
Transcription factor involved in erythroid differentiation. Involved in transcriptional activation of the globin gene.
Synonyms: C10orf137; DKFZp586F1019; FLJ21617
Tractability: PROTAC: ubiquitination databases record sites on it.
Gene: Protein-coding gene on chromosome 10 (125,719,515 to 125,764,143, forward strand). Ensembl gene ENSG00000107938.
Subcellular location: Nucleus
Subcellular location (Human Protein Atlas): Nucleoplasm; Centrosome; Cytosol
Gene Ontology:
Molecular function: protein binding
Biological process: positive regulation of DNA-templated transcription
Cellular component: nucleus
Genetic constraint (gnomAD): Loss-of-function variants: 59 observed, 138.35 expected, observed/expected ratio (o/e) 0.43, 90% interval 0.34 to 0.53. The upper end of that interval is the gene's LOEUF score, 0.53, which puts it in group 2 of 6, group 1 being the genes least tolerant of losing a copy. Missense variants: 1,067 observed, 1,467.7 expected, observed/expected ratio (o/e) 0.73, 90% interval 0.69 to 0.76. Synonymous variants: 498 observed, 537.04 expected, observed/expected ratio (o/e) 0.93, 90% interval 0.86 to 1.
Homologues: Orthologues: chimpanzee EDRF1 (99% identical), macaque EDRF1 (99% identical), dog EDRF1 (96% identical), pig EDRF1 (95% identical), rat Edrf1 (93% identical), mouse Edrf1 (93% identical), guinea pig EDRF1 (91% identical), rabbit EDRF1 (86% identical), tropical clawed frog edrf1 (75% identical), zebrafish edrf1 (69% identical), Drosophila melanogaster CG6511 (35% identical).
Diseases named in the same sentence as EDRF1 in open-access papers:
EDRF1 is named in the same sentence as 4 diseases in open-access papers, as found by Europe PMC text mining. Sharing a sentence is not in itself a finding about the gene and the disease. The quoted sentences say what the papers report.
COVID-19 (1 paper, 2023). A disease caused by infection with severe acute respiratory syndrome coronavirus 2. "These publications indicate that the taste or smell loss in COVID-19 patients is related to in situ odor dysfunction, which the gene EDRF1 also participated in through the GATA-1-mediated pathway." (PMID 36983953, 2023).
dengue virus infections (1 paper, 2023). "Based on these reports we framed the hypothesis that EDRF1, GATA1, and spectrins might be affected during the dengue virus infection." (PMID 37534186, 2023). "Hence, it is concluded that cleavage of the EDRF1, a nuclear transcription factor, by NS2BNS3 of dengue virus, and the NS3-mediated mitochondrial dysfunction contribute to the reduced number of platelet formation (thrombocytopenia) during dengue virus infections." (PMID 37534186, 2023).
hypokalaemia (1 paper, 2009). "Furthermore, hypokalaemia causes alterations in the levels of vasoactive mediators: an increase in vasoconstrictor stimuli (ACE, ET-1 and subtype B α-adrenergic receptors) and a reduction in vasodilatory stimuli (EDRF-1 and PGE2)." (PMID 19144110, 2009).
Thrombocytopenia (1 paper, 2023). A reduction in the number of circulating thrombocytes. "Hence, we conclude that NS2BNS3-mediated EDRF1 cleavage and the NS3-led mitochondrial dysfunction account for thrombocytopenia." (PMID 37534186, 2023). "Hence the cleavage of EDRF1 observed in the present study led to decreased levels of GATA1 and subsequently to fewer spectrins and finally to the reduced number of platelets, i.e., thrombocytopenia." (PMID 37534186, 2023).